BAIAP2 (BAR/IMD domain containing adaptor protein 2)
Description:
Adapter protein that links membrane-bound small G proteins to cytoplasmic effector proteins. Necessary for CDC42-mediated reorganization of the actin cytoskeleton and for RAC1-mediated membrane ruffling. Involved in the regulation of the actin cytoskeleton by WASF family members and the Arp2/3 complex. Plays a role in neurite growth, neuronal differentiation and neuronal migration. Acts syngeristically with ENAH to promote filipodia formation. Plays a role in the reorganization of the actin cytoskeleton in response to bacterial infection. Participates in actin bundling when associated with EPS8, promoting filopodial protrusions.
Synonyms: FLAF3; IRSp53; BAP2; WAML; DEE120
Tractability: Small molecule: a structure with a bound ligand is known. Antibody: its Gene Ontology location is reachable by antibodies, with high confidence; UniProt places it where antibodies can reach, with medium confidence; the Human Protein Atlas places it where antibodies can reach. PROTAC: ubiquitination databases record sites on it; its protein half-life has been measured.
Gene: Protein-coding gene on chromosome 17 (81,035,122 to 81,117,434, forward strand). Ensembl gene ENSG00000175866.
Subcellular location: Cytoplasm; Membrane; Cell projection, filopodium; Cell projection, ruffle; Cytoplasm, cytoskeleton
Subcellular location (Human Protein Atlas): Cytosol; Plasma membrane
Pathways (Reactome):
Signal Transduction: CDC42 GTPase cycle; RAC1 GTPase cycle; RAC3 GTPase cycle; RHO GTPases Activate WASPs and WAVEs; VEGFA-VEGFR2 Pathway
Disease: FCGR3A-mediated phagocytosis
Immune System: Regulation of actin dynamics for phagocytic cup formation
Gene Ontology:
Molecular function: cadherin binding involved in cell-cell adhesion; identical protein binding; proline-rich region binding; protein binding; cytoskeletal anchor activity; PDZ domain binding; scaffold protein binding; transcription coregulator binding
Biological process: filopodium assembly; neuron projection morphogenesis; regulation of actin cytoskeleton organization; actin crosslink formation; actin filament bundle assembly; axonogenesis; insulin receptor signaling pathway; neuron differentiation; neuron migration; positive regulation of actin filament polymerization; regulation of cell shape; cell-cell adhesion; cellular response to epidermal growth factor stimulus; cellular response to L-glutamate; plasma membrane organization; positive regulation of dendritic spine morphogenesis; positive regulation of excitatory postsynaptic potential; positive regulation of neuron projection development; protein localization to synapse; regulation of modification of postsynaptic actin cytoskeleton; regulation of postsynapse organization
Cellular component: actin cytoskeleton; adherens junction; cytoplasmic side of plasma membrane; cytosol; extracellular exosome; plasma membrane; cytoplasm; cytoskeleton; dendritic shaft; dendritic spine; dendritic spine cytoplasm; excitatory synapse; filopodium; glutamatergic synapse; lamellipodium; membrane; microtubule; neuron projection branch point; neuron projection terminus; neuronal cell body; postsynapse; postsynaptic cytosol; postsynaptic density; postsynaptic density, intracellular component; presynapse; and 4 more
Genetic constraint (gnomAD): Loss-of-function variants: 17 observed, 57.23 expected, observed/expected ratio (o/e) 0.3, 90% interval 0.2 to 0.45. The synonymous counts are far from expectation, so gnomAD's model fits this gene poorly and the ratio says little. Missense variants: 609 observed, 703.71 expected, observed/expected ratio (o/e) 0.87, 90% interval 0.81 to 0.93. Synonymous variants: 385 observed, 301.31 expected, observed/expected ratio (o/e) 1.28, 90% interval 1.17 to 1.39.
Homologues: Orthologues: macaque BAIAP2 (99% identical), chimpanzee BAIAP2 (96% identical), mouse Baiap2 (96% identical), guinea pig BAIAP2 (96% identical), rat Baiap2 (96% identical), pig BAIAP2 (94% identical), dog BAIAP2 (90% identical), tropical clawed frog baiap2 (76% identical), zebrafish baiap2a (64% identical), zebrafish baiap2b (45% identical), Drosophila melanogaster IRSp53 (28% identical). Paralogues in human: BAIAP2L1 (39% identical), BAIAP2L2 (27% identical).
Diseases named in the same sentence as BAIAP2 in open-access papers:
BAIAP2 is named in the same sentence as 53 diseases in open-access papers, as found by Europe PMC text mining. Sharing a sentence is not in itself a finding about the gene and the disease. The quoted sentences say what the papers report.
schizophrenia (9 papers, 2020 to 2024). A major psychotic disorder characterized by abnormalities in the perception or expression of reality. "BAIAP2 has also been linked to a variety of psychiatric disorders, including autism spectrum disorder, schizophrenia, and attention-deficit/hyperactivity disorder." (PMID 37234209, 2023). "The abnormal expression or function of BAIAP2 is closely associated with autism, attention-deficit/hyperactivity disorder, and schizophrenia." (PMID 37234209, 2023). "This could be applicable to brain diseases other than ASD, given that IRSp53/BAIAP2 has been implicated in schizophrenia and ADHD, in addition to ASD." (PMID 37730842, 2023). "Recent studies have associated IRSp53/Baiap2 with various psychiatric disorders, including autism spectrum disorder (ASD), attention-deficit/hyperactivity disorder (ADHD) and schizophrenia." (PMID 38532383, 2024). "IRSp53 (also known as BAIAP2) is an abundant excitatory postsynaptic scaffolding protein implicated in autism spectrum disorders (ASD), schizophrenia, and attention-deficit/hyperactivity disorder (ADHD)." (PMID 32116566, 2020). "IRSp53 (or BAIAP2) is an abundant excitatory postsynaptic scaffolding/adaptor protein that is involved in actin regulation and has been implicated in autism spectrum disorders, schizophrenia, and attention-deficit/hyperactivity disorder." (PMID 35982261, 2022). "IRSp53/BAIAP2-related mutations in humans have been implicated in ASD, ADHD, and schizophrenia." (PMID 36317872, 2022).
cognitive deficits (8 papers, 2014 to 2025). "BAIAP2 (also known as IRSp53), a brain‐specific insulin receptor tyrosine kinase substrate which has been shown to be involved in impaired memory, learning, and other cognitive deficits in mouse models of Alzheimer's." (PMID 38263575, 2024). "BAIAP2 deficiency leads to defective actin/membrane regulation in dendritic spines, NMDA receptor dysfunction, and social and cognitive deficits." (PMID 37234209, 2023). "In conclusion, in the present study, we demonstrated that BAIAP2 can prevent stress-induced depression-like behaviors and cognitive impairment in mice, strongly suggesting its potential in the treatment of depression and perhaps other stress-induced psychiatric disorders." (PMID 37234209, 2023). "We found that overexpressing BAIAP2 in the hippocampus of CMS-treated mice not only alleviated the CMS-induced decrease in dendritic spine density but also largely prevented the consequent depression-like behavior and concomitant cognitive impairment." (PMID 37234209, 2023). "Previous studies have indicated that mice lacking Baiap2 exhibit enhanced activation of the N-methyl-D-aspartate receptor (NMDAR), resulting in social and cognitive deficits." (PMID 38532383, 2024).
attention deficit-hyperactivity disorder (7 papers, 2014 to 2024). A disorder characterized by a marked pattern of inattention and/or hyperactivity-impulsivity that is inconsistent with developmental level and clearly interferes with functioning in at least two settings (e.g. at home and at school). "Genetic variations in BAIAP2 were also associated with attention-deficit hyperactivity disorder and autism." (PMID 24392092, 2014). "BAIAP2 has been shown to be potentially involved in the etiology of attention deficit/hyperactivity disorder." (PMID 34035472, 2021). "Additionally, six genes displaying at least differential expression among hemispheres (BAIAP2, DAPPER1, LMO4, NEUROD6, ATP2B3, and ID2) in a case-control association study in an initial Spanish sample of ADHD (Attention Deficit Hyperactivity Disorder) patients and control subjects." (PMID 30081481, 2018).
autism (7 papers, 2014 to 2025). Persistent deficits in social interaction and communication and interaction as well as a markedly restricted repertoire of activity and interest as well as repetitive patterns of behavior. "In addition, it was shown to play an important regulatory role in the hippocampal expression of Baiap2, which is involved in dendritic spine formation and is downregulated in neurodevelopmental disorders such as autism and hyperactivity syndromes." (PMID 40868063, 2025).
autism spectrum disorder (5 papers, 2019 to 2024). A spectrum of developmental disorders that includes autism, and Asperger syndrome. "To specify, BAIAP2 encodes brain-specific angiogenesis inhibitor - binding protein that is involved in neurodevelopmental/ neurite outgrowth network, and its genotype and expression were associated with autism spectrum disorders (ASD) and attention-deficit/hyperactivity disorder (ADHD)." (PMID 30606219, 2019).
Anxiety (3 papers, 2020 to 2023). Intense feelings of nervousness, tension, or panic often arise in response to interpersonal stresses. "To test this, we upregulated BAIAP2 expression in the hippocampus of mice and assessed the effect on dendritic spine density and depression- and anxiety-like behaviors." (PMID 37234209, 2023). "Mice exposed to CMS exhibited depression- and anxiety-like behaviors accompanied by decreased levels of BAIAP2 in the hippocampus." (PMID 37234209, 2023). "The expression of BAIAP2 was downregulated in the hippocampus of CMS-exposed mice, while the upregulation of BAIAP2 prevented the depression- and anxiety-like behavior induced by CMS." (PMID 37234209, 2023). "Given that, in mice, the deletion of BAIAP2 and its re-expression after deletion has been shown to affect cognitive ability but not anxiety-like behavior, we next focused on the potential effects of BAIAP2 overexpression on memory and depression-like behavior in CMS-exposed mice." (PMID 37234209, 2023).
depression (3 papers, 2023 to 2025). "Notably, in addition to the brain, BAIAP2 is also expressed in epithelial tissues, including vascular epithelial cells, and it is now known that people with depression are at an increased risk of cardiovascular disease." (PMID 37234209, 2023). "Combined, these results demonstrated that overexpressing BAIAP2 in the hippocampus can prevent depression-like behavior and memory impairment induced by CMS in mice." (PMID 37234209, 2023). "Consistent with this, we found that BAIAP2 also plays a protective role against depression-like phenotypes in mice." (PMID 37234209, 2023). "In the present study, we explored the role of hippocampal BAIAP2 in the pathophysiology of depression." (PMID 37234209, 2023). "Our findings shed light on the role of BAIAP2 in depression and highlight the therapeutic potential of targeting hippocampal BAIAP2 for the treatment of this condition." (PMID 37234209, 2023). "Our findings indicate that hippocampal BAIAP2 can prevent stress-induced depression-like behavior and may be a promising target for the treatment of depression or other stress-related diseases." (PMID 37234209, 2023). "Consistent with the in vitro data, the AAV-mediated overexpression of BAIAP2 in the hippocampus of mice significantly inhibited CMS-induced depression-like behavior, concomitant with increases in dendritic spine density and the expression of GluA1 and SYN1 in hippocampal regions." (PMID 37234209, 2023). "Despite this, BAIAP2 remains a potential therapeutic target for depression." (PMID 37234209, 2023). "Despite studies showing that BAIAP2 has a neuroprotective function, it is unknown whether this protein in the hippocampus has an impact on depression." (PMID 37234209, 2023). "However, the role of BAIAP2 in depression remains poorly understood." (PMID 37234209, 2023). "Specifically, we investigated whether BAIAP2 expression is altered in mice subjected to CMS, assessed the effect of BAIAP2 on corticosterone (CORT)-induced injury in HT22 cells, and investigated whether BAIAP2 can block CMS-induced depression-like behavior in mice." (PMID 37234209, 2023).
glioblastoma (3 papers, 2019 to 2023). The most malignant astrocytic tumor (WHO grade IV). "Brain-specific angiogenesis inhibitor (BAI1)-binding protein-BAIAP2 is a member of the adhesion GPCR subfamily, highly expressed in the normal brain tissue and epigenetically silenced in glioblastoma." (PMID 31717665, 2019).
breast carcinoma (2 papers, 2016 to 2025). "Rs142882938, a deletion/insertion variation (−/T), explained the association of BAIAP2 with all breast cancer and ER+ breast cancer." (PMID 27942580, 2016). "BAIAP2 was associated with overall and ER+ breast cancer; CALM2 with overall breast cancer; CSNK2A1 with ER+ breast cancer; and BRAF, BAD, and MAPK3 with ER− breast cancer." (PMID 27942580, 2016). "The most significant gene associations (P⩽0.01) were BAIAP2 and CALM2 for overall breast cancer; BAIAP2 and CSNK2A1 for ER+ breast cancer; and BRAF, BAD, and MAPK3 for ER− breast cancer." (PMID 27942580, 2016).
diabetes (2 papers, 2021 to 2025). "Additionally, 7 CpG sites annotated to MAN2A2, ABCG1, DENND3, NCOR2, BAIAP2 and CPT1A were linked to changes in diabetes status." (PMID 39827095, 2025). "Notably, among the seven CpG sites liked to the diabetes progression, five showed a negative correlation with gene expression levels, including cg23436042, cg11183227 (MAN2A2), cg06500161 (ABCG1), cg06710464 (BAIAP2), and cg17058475 (CPT1A), while cg08788930 (DENND3) and cg11311053 (NCOR2) did not." (PMID 39827095, 2025).
Allergy (1 paper, 2023). An allergy is an immune response or reaction to substances that are usually not harmful. "Here, we detected a differential signal in only one gene, BAIAP2, associated with the 04810 pathway (“Regulation of actin cytoskeleton”), but found no differential methylation in the context of allergy overall." (PMID 37762215, 2023). "The signal in the BAIAP2 gene was detected in the context of anaphylaxis, but no significant differential methylation was found in the context of allergy." (PMID 37762215, 2023).
cognitive decline (1 paper, 2021). "Genes involved in neuronal postsynaptic density were enriched among DMRs associated with the rate of cognitive decline as measured by mPACCtrailsB, and this enrichment was driven by DMRs annotated to BNIP3, NTRK2, and BAIAP2." (PMID 34654479, 2021).
colorectal cancer (1 paper, 2023). A primary or metastatic malignant neoplasm that affects the colon or rectum. "The major risk factor for a bad outcome in colorectal cancer is abnormal localization of BAIAP2 on the cell membrane." (PMID 36761433, 2023).
esophagus squamous cell carcinoma (1 paper, 2023). "A bioinformatic study constructed a prognostic model in esophagus squamous cell carcinoma including BAIAP2." (PMID 37179366, 2023).
fibrosarcoma (1 paper, 2023). A malignant mesenchymal fibroblastic neoplasm affecting the soft tissue and bone. "BAIAP2 also positively regulates the motility and invasive ability of fibrosarcoma cells, suggestive of its importance in the metastatic behavior of tumor cells." (PMID 37234209, 2023).
kidney stone (1 paper, 2025). "Five of these protein ratio pairs positively promote kidney stone development: BAIAP2/MME protein level ratio, GRPEL1/MME protein level ratio, HLAE/IL15 protein level ratio, CEACAM1/GGT1 protein level ratio and BTN2A1/IL18BP protein level ratio." (PMID 40673688, 2025).
psoriasis (1 paper, 2020). An autoimmune condition characterized by red, well-delineated plaques with silvery scales that are usually on the extensor surfaces and scalp. "BAIAP2 has been shown to control the expression of the proinflammatory cytokines IL-6 and IL-1α, and PRKCZ has been noted to play a role in controlling inflammatory dermal mesenchymal stem cells in psoriasis, a T cell-mediated disease." (PMID 32117236, 2020).
cancer (8 papers, 2013 to 2025). A tumor composed of atypical neoplastic, often pleomorphic cells that invade other tissues. "In addition, interactions of BAIAP2 with the WAVE regulatory complex control highly dynamic processes involved in cholesterol clearance, embryogenesis, neuron morphogenesis and plasticity, immune cell activation, chemotaxis, fibrosis, and cancer invasion and metastasis." (PMID 38984353, 2024).
tumor (8 papers, 2013 to 2025). "Finally, we demonstrated that PROX1 and other vascular factors, such as VEGFC (vascular endothelial growth factor C), BAIAP2 (BAI1 associated protein 2), FGF2 (fibroblast growth factor 2), and PLAT (plasminogen activator) are differently expressed in FTC human tissues compared to non-tumor tissues." (PMID 31717665, 2019).
infection (7 papers, 2010 to 2025). The state of being infected such as from the introduction of a foreign agent such as serum, vaccine, antigenic substance or organism. "Furthermore, our RT-qPCR data showed that both predicted miR-29a targets AKT3 and BAIAP2 possessed an anti-correlated trend during early infection." (PMID 23826261, 2013). "For validation of outlined interactions and to legitimate calculated miR-29a-target interactions and to prove biological significance, we examined the expression of miR-29a, AKT3, BAIAP2, COL4A1, VCL, CAV2 and CDC42 over the course of infection by means of RT-qPCRs." (PMID 23826261, 2013).
psychiatric disorder (2 papers, 2023 to 2024). A disorder characterized by behavioral and/or psychological abnormalities, often accompanied by physical symptoms. "Brain-specific angiogenesis inhibitor 1-associated protein 2 (BAIAP2), a postsynaptic scaffold protein in excitatory synapses important for synaptic plasticity, is highly expressed in the hippocampus and has been implicated in several psychiatric disorders." (PMID 37234209, 2023).
BAIAP2 also shares sentences with these, for which no sentence is quoted: brain disorder (2 papers); glioma (2); melanoma (2); neuroblastoma (2); neurodevelopmental disorder (2); alcohol dependence (1); anaphylaxis (1); breast tumors (1); cardiovascular disease (1); chronic obstructive pulmonary disease (1); colon cancer (1); colorectal adenocarcinoma (1); cyst (1); dementia (1); diffuse midline glioma (1); dyslipidemia (1); endothelial dysfunction (1); epilepsy (1); Follicular Thyroid Cancer (1); Hereditary Sensory Autonomic Neuropathy (1); HIV-1 infection (1); Hyperglycemia (1); invasive breast carcinoma (1); memory impairment (1); neurological disease (1); non-Hodgkin lymphoma (1); Parkinson disease (1); prediabetes (1); reticulum cell sarcoma (1); Sepsis (1).
A further 2 diseases each share a sentence with BAIAP2 in 1 paper.